INS (insulin)
Diseases named in the same sentence as INS in open-access papers (continued):
Sharing a sentence is not in itself a finding about the gene and the disease.
Hyperinsulinemia (continued). "Given the increased incidence of CRC caused by hyperinsulinemia, whether insulin analogs could become hopeful alternative to insulin therapy still urgently needs more clinical trials for further verification." (PMID 35296101, 2022). "IR also causes hyperinsulinemia, i.e., the over-production of insulin by βbeta cells." (PMID 35163806, 2022). "Consumption of the “modern” Western diet, over-nutrition, genetic background, decreased hepatic insulin clearance, and fetal/metabolic programming may increase insulin secretion, thereby causing chronic hyperinsulinemia." (PMID 35897752, 2022). "Hyperinsulinemia caused by IR and reflecting impaired insulin action may potentiate the inflammatory response, as inflammatory pathways are linked to insulin signaling." (PMID 36498989, 2022). "Similarly, in the case of insulin, there have been reports of both an anti-inflammatory role as well as that hyperinsulinemia seems to cause an exaggeration of oxidative stress." (PMID 35742776, 2022). "The rise of maternal blood glucose will cause hyperinsulinemia in the fetus, and insulin cannot be transported through the placenta, which will promote the deposition of liver glycogen, protein synthesis, and fat deposition, thus promoting the growth and development of the fetus." (PMID 36407306, 2022). "In horses and ponies with ID, hyperinsulinemia is most pronounced in association with carbohydrate ingestion; therefore, understanding and controlling the postprandial insulin response is critical to developing effective laminitis prevention and management strategies for horses with ID." (PMID 35906619, 2022). "However, its potential role in the pathogenesis of depression and the positive association of hyperinsulinemia with depression support the correlation between lower insulin levels and higher MCS." (PMID 35956337, 2022). "IR can cause hyperinsulinemia, namely higher insulin levels in the circulating system." (PMID 35941598, 2022). "siMSscore correlated with associated factors of MS: hyperinsulinemia and IR (insulin, mean insulin value, HOMA-IR), ALT, GGT, FLI, uric acid (p < 0.01) in both groups as well as with CRP (p < 0.01) in group I, p = 0.005 in group II, log CRP (p < 0.01) in group I and p = 0.003 in group II." (PMID 36685849, 2022). "Peripheral hyperinsulinemia is associated with reduced insulin transport into the brain, and central hypoinsulinemia promotes neurodegeneration through reduction of neurotrophic factors; greater retention of amyloid beta, a pathological feature of AD; and through other mechanisms." (PMID 35458181, 2022). "Additionally, prolonged fasting contributes to more extended periods where insulin levels are low, assisting in weight loss and improved insulin sensitivity through hyperinsulinemia reduction." (PMID 36465743, 2022). "Therefore, PRL excess is associated with postprandial hyperinsulinemia and exceeding insulin secretory response to glucose in humans; improvement in FG, FI and related indices is achieved during DAs therapy." (PMID 36237192, 2022). "Notably, LDL treatment increased mRNA levels and insulin secretion; this hyperinsulinism condition was associated with the transcription factor PDX-1." (PMID 36005626, 2022). "Genes, consumption of the “modern” Western diet, over-nutrition and other environmental factors may increase insulin secretion, decrease insulin pulses and/or reduce hepatic insulin clearance and thereby cause hyperinsulinemia." (PMID 34360563, 2021). "Insulin may contribute to blood pressure regulation and insulin resistance and compensatory hyperinsulinemia is suggested to be a major risk factor for the development of hypertension." (PMID 34578814, 2021). "Since pNETs in RT2 mice cause hyperinsulinemia, we tested whether plasma insulin levels correlated with tumor burden." (PMID 34199469, 2021).
Hyperinsulinemia (continued). "Genetic background, consumption of the “modern” Western diet and over-nutrition may increase insulin secretion, decrease insulin pulses and/or reduce hepatic insulin clearance, thereby causing hyperinsulinemia." (PMID 34360563, 2021). "Therefore, post-burn, insulin secretion is augmented (causing hyperinsulinemia), but less than one would expect in such a hypermetabolic state." (PMID 34068151, 2021). "IR, which causes insulin dysfunction in DM II or MetS, leads to prolonged hyperinsulinemia." (PMID 34208601, 2021). "Apparently healthy persons with hyperinsulinemia and a normal glucose tolerance showed an increase in risk factors for coronary artery disease, as compared with a well-matched group of healthy subjects with normal insulin levels." (PMID 34360563, 2021). "We previously demonstrated that IH induces hyperinsulinemia and associated altered insulin signaling in adipose tissue, liver, and skeletal muscle, but impact of IH on cardiac insulin signaling and functional/structural consequences remains unknown." (PMID 33682327, 2021). "That indirectly suggests that hyperinsulinemia may be a risk factor for PC, and thus indicates insulin secretion inducing features of SU as a main cancerogenic factor." (PMID 33921222, 2021). "In conclusion, the effect of AAPs on β-cells insulin secretion is still controversial and the hyperinsulinemia caused by AAPs as reported by several papers could be due to peripheral insulin resistance and/or β-cells overstimulation." (PMID 33800403, 2021). "Hyperinsulinemia in combination with decreased GH secretion causes a shift of the insulin : GH ratio towards insulin (as a consequence of increased insulin secretion and/or reduced hepatic insulin clearance) and away from GH (as a consequence of the suppression of GH secretion)." (PMID 34360563, 2021). "For example, insulin variants Wakayama and Chicago (i.e., classical insulinopathies ValA3→Leu and PheB25→Leu respectively) markedly impede receptor binding in association with mutant hyperinsulinemia." (PMID 34659132, 2021). "In this concept, the stimulating effects of hyperinsulinemia in the periphery are dampened by the development of insulin resistance in muscles and fat cells, the latter directly caused by an overexposure of the peripheral tissues to endogenous insulin." (PMID 34360563, 2021). "However, the metabolic changes driving insulin secretion in the pancreatic β-cell, which causes hyperinsulinemia in this latter model, remains to be identified." (PMID 33712379, 2021). "The combined action of the three causes hyperinsulinemia, and then excessive insulin acts on the liver to hinder the synthesis of SHBGs, which can increase the free testosterone level and inhibit the production of insulin-like growth factor 1 binding protein (IGFBP-1)." (PMID 34992582, 2021). "Nevertheless, these correlations do not provide a clear mechanistic understanding of the relationship between elevated levels of insulin and Hcy and it is still unknown whether hyperhomocysteinemia is a consequence or a cause of hyperinsulinemia." (PMID 32645905, 2020). "Liquid sucrose ingestion causes hyperinsulinemia and alters insulin sensitivity indices." (PMID 32086249, 2020). "In the context of previously published studies, these results suggest that Black women may be more susceptible to the cancer promoting effects of hyperinsulinemia, due to higher levels of circulating insulin and higher ratio of tumor IR/IGF-1R expression." (PMID 32393319, 2020). "Iron overload has been proven to disturb insulin signaling and cause hyperinsulinemia." (PMID 32546165, 2020). "Moreover, chronic inflammation and oxidative stress, as two hallmarks of PCOS, are closely related in PCOS women and cause impaired insulin action and hyperinsulinemia leading to anovulation." (PMID 32005271, 2020).
Hyperinsulinemia (continued). "The synergistic effect of relative hyperinsulinemia (from the previous exogenous injection) and exercise-induced insulin-independent pathways cause the uptake of glucose into myocytes to exceed hepatic glucose release and a decline in blood glucose during continuous steady-state exercise." (PMID 33193089, 2020). "Hyperinsulinemia has been consistently associated with increased breast cancer risk, and metformin is known to provide both direct and indirect effect in reducing cell proliferation through controlling insulin levels and blood glucose." (PMID 32369516, 2020). "Pharmacologic reduction in insulin levels may ameliorate complications associated with hyperinsulinemia and hyperandrogenemia and appear to offer a therapeutic modality for PCOS." (PMID 32252239, 2020). "Additionally, elevated C-Peptide and pro-insulin levels have been shown to have greater diagnostic accuracy for the diagnosis of endogenous hyperinsulinism than insulin levels." (PMID 32992761, 2020). "Dysfunction in the insulin signaling pathway may cause compensatory hyperinsulinemia, thereby generating resistance to insulin." (PMID 31137715, 2019). "Additionally, cav-1-deficient mice had higher plasma insulin levels and postprandial hyperinsulinemia under fasting or high-fat diet conditions." (PMID 31728004, 2019). "In severely diabetic fat sand rats (P. obesus), which exhibit extreme hyperinsulinemia, compensation depends solely on insulin overproduction; consequently, rapamycin may cause decompensation." (PMID 31406105, 2019). "Hyperinsulinemia associated with IR and known mitogenic activity of insulin of insulin could be responsible for the process." (PMID 31795960, 2019). "An increase in EGF during marked hyperinsulinemia could also be associated with the onset of lamellar damage initiated by insulin, with EGF initiating a wound healing response as postulated above." (PMID 31805097, 2019). "Metformin, GLP-1 receptor agonists, and chemical chaperones could have a dual effect on both the underlying insulin dysregulation and hyperinsulinemia that triggers EL, and on laminitis pathogenesis at the lamellar tissue level." (PMID 30630474, 2019). "Hyperinsulinemia is a risk factor for pancreatic cancer, but the function of insulin in carcinogenesis is unclear, so this study aimed to elucidate the carcinogenic effects of insulin and the synergistic effect with the KRAS mutation in the early stage of pancreatic cancer." (PMID 30838710, 2019). "Moreover, plasma levels of insulin and C-peptide, markers of hyperinsulinemia, predict risk of digestive system cancers, including colorectal, gastric, and pancreatic cancers." (PMID 30740588, 2018). "Hence, HFD-triggered peripheral hyperinsulinemia to some extent can initially provokes insulin deficiency in the brain, leading to lower expression of insulin degrading enzyme and less degradation (accumulation) of Aβ." (PMID 30483273, 2018). "Subsequently, an exaggerated second-phase insulin response causes chronic hyperinsulinemia." (PMID 30602666, 2018). "It is conceivable that during early weight loss, SDV alters the set point due to reversal (or normalization) of the underlying hyperinsulinemia in Mc4r−/− mice as a result of denervation of the insulin-secreting cells of the pancreas, and presumably depletion of hepatic glycogen stores." (PMID 29545738, 2018). "IR and compensatory hyperinsulinemia cause hyperandrogenemia in women and androgen excess per se might also impair insulin action." (PMID 29552281, 2018). "T2DM it is a progressive disease including insulin resistance, β-cell hyperplasia and/or β cell hypertrophy, that mediates a compensatory insulin secretion and subsequently hyperinsulinemia, pancreatic β cell dysfunction and a loss of cell identity or de-differentiation." (PMID 30386301, 2018).
Hyperinsulinemia (continued). "Dietary fiber from non-refined grains and other plant sources might also have a beneficial impact on bone through decreasing glycemic load and inhibiting hyperinsulinemia which in turn prevents urinary calcium loss induced by insulin." (PMID 29490662, 2018). "The resulting hyperinsulinemia and increased offspring growth may lead to an insulin secretory defect, contributing to a lifelong higher risk of developing overweight and T2DM, as shown in animal studies." (PMID 30372451, 2018). "Indeed, insulin elevation affects leptin signaling and hyperinsulinemia can be associated to the development of leptin resistance." (PMID 29740277, 2018). "In horses and ponies, insulin dysregulation leading to hyperinsulinemia may be associated with increased risk of laminitis, and prolonged infusion of insulin can induce the condition." (PMID 30519508, 2018). "In addition, previous studies have shown that hyperinsulinemia is associated with hypertension and dyslipidemia, likely due to insulin-mediated sympathetic stimulation and IR in peripheral tissues." (PMID 29789568, 2018). "By contrast and puzzling clinicians, the metabolomic signature of some pathologies connected to an increased risk of cancer, such as prolonged hyperinsulinemia in insulin-resistant patients, is identified by elevated plasma levels of the same branched-chain amino acids." (PMID 30453654, 2018). "On the other hand, hyperinsulinemia (consequential to insulin-resistant states) may also cause medial hypertrophy, which is included in the intima-media complex." (PMID 29590246, 2018). "Reducing hyperinsulinemia is a treatment goal for horses with insulin-associated laminitis." (PMID 29404215, 2018). "Preliminary studies suggest that the reduced insulin secretion associated with LC and low-GI diets may attenuate these adaptations, facilitating long-term weight-loss maintenance and reducing hyperinsulinemia (the carbohydrate-insulin model)." (PMID 28338608, 2017). "Taken together, differential effects of TA-1887 and insulin treatment on endothelial function may be due in part to differences in vascular inflammation caused by hyperinsulinemia as blood glucose levels improve, an event with consequences for mortality." (PMID 28900540, 2017). "Our data suggest that hyperinsulinemia secondary to decreased insulin sensitivity, gauged as elevated fasting and post-glucose insulin AUC0−120, may be an intermediary mechanism underlying the association between NC and MSNA in men." (PMID 28428756, 2017). "A previous study showed that the transition from NGT to IGR is associated with the deterioration of insulin sensitivity, but glucose tolerance in this process is only mildly impaired because of the compensatory increase in insulin secretion and resultant hyperinsulinemia." (PMID 28199386, 2017). "Bolstering this function of CEACAM1, defective hepatic insulin clearance and subsequently, chronic hyperinsulinemia develops in mice with global null mutation (Cc1−/−) or with liver-specific overexpression of the dominant-negative phosphorylation-defective inactive isoform of Ceacam1 (L-SACC1)." (PMID 28396653, 2017). "Similarly, electrolytic destruction of VMH was shown to cause an increase in circulating insulin levels and this hyperinsulinemia was more pronounced following glucose infusion." (PMID 27598259, 2016). "Due to the association between hyperinsulinemia and laminitis in the horse, identification of individuals with an exaggerated postprandial insulin response using OGTT may enable better management of horses and ponies at risk for pasture-associated laminitis." (PMID 27766982, 2016). "It is possible that disruption of normal insulin signaling (hyperinsulinemia, insulin resistence or absolute insulin deficiency) may play a significant role in the pathogenesis of diabetic complications." (PMID 27434075, 2016). "GDM may predispose to fetal hyperinsulinemia and, in our study, cord blood insulin did suggest such an association." (PMID 27196053, 2016).
Hyperinsulinemia (continued). "Although there is uncertainty whether increased blood glucose concentration in the early neonatal period does induce an increase in insulin production, transient neonatal hyperinsulinism is the likely mechanism underlying most transient neonatal hypoglycaemia." (PMID 27780197, 2016). "A meta-analysis of earlier population studies examining insulin levels and cancer incidence confirmed that hyperinsulinemia and high C-peptide levels (another measure of insulin production) are correlated with an increased risk of breast cancer as well as colorectal and pancreatic cancer." (PMID 26029167, 2015). "Given the mitogenic and antiapoptotic effects of insulin, the reduction in systemic levels may be critical to the anticancer effects of metformin, particularly in cancers associated with obesity and hyperinsulinemia, such as those of the breast and colon." (PMID 25849721, 2015). "The possible potential mechanism of how high insulin levels could enhance weight gain is that hyperinsulinemia may cause a greater energy intake to excessive weight gain in children." (PMID 26047327, 2015). "Future studies should examine whether hyperinsulinemia and exogenous insulin have a causal role in disease progression and whether better insulin control results in decreased incidence or improved outcomes in endometrial cancer." (PMID 26134033, 2015). "Subcutaneous injection of insulin results in significantly higher levels of circulating insulin in the systemic circulation than does endogenous insulin secretion, thereby possibly amplifying the links between hyperinsulinemia and cancer risk through excessive insulin binding to the IGF-I receptor." (PMID 25978841, 2015). "However, due to the complex pathophysiology of hyperinsulinemia, the causative role of excess insulin/IGF signaling has remained elusive." (PMID 24795642, 2014). "The molecular mechanisms for these associations are unknown, but chronic sustained hyperinsulinemia in these insulin-resistant patients appears to play a role in the carcinogenesis." (PMID 24911052, 2014). "In addition, iron is a potent pro-oxidant that increases cellular oxidative stress, causing inhibition of insulin internalization and action, which results in hyperinsulinemia, IR, and abnormal β-cell function through iron toxicity." (PMID 24764731, 2014). "The bromocriptine-induced reduction in liver and adipose fat content is associated with and may derive in part from reductions of hyperinsulinemia, liver lipogenic responsiveness to insulin and pro-inflammatory pathways that potentiate lipogenic activity." (PMID 25937836, 2014). "This hypothesis is supported by our interesting results showing an independent association of androstenedione/free testosterone-ratio with hyperinsulinemia, IR, and insulin sensitivity." (PMID 25310562, 2014). "Since renal disease is associated with elevated plasma insulin values, it is also possible that the prevention of hyperinsulinemia may also be a factor in reducing the development of kidney disease." (PMID 25473963, 2014). "Given that hyperinsulinemia has been identified as an independent risk factor for pancreatic cancer, it is imperative to understand how changes in insulin signalling may promote cancer progression." (PMID 25373319, 2014). "In other studies of T2DM, cognitive deficits and structural brain atrophy were linked to cerebral hypoperfusion and altered vascular reactivity, and disrupted default-mode network connectivity was associated with peripheral hyperinsulinemia, insulin resistance, and white matter integrity." (PMID 25071557, 2014). "This, associated withthe increased pancreatic β-cell function and the reducedhepatic insulin clearance we observed, mayexplain hyperinsulinemia in those PCOS patientswho smoke and their higher risk for progression totype-2 diabetes and CV diseases." (PMID 24520500, 2014).